USP22 (ubiquitin specific peptidase 22)
Diseases named in the same sentence as USP22 in open-access papers (continued):
Sharing a sentence is not in itself a finding about the gene and the disease.
breast carcinoma (continued). "Indeed, reconstitution of FoxM1 expression fully restored the endogenous integrin b1 expression in both USP22-null 4T1 and L2G+ TN1 breast cancer cells as determined by western blotting and qRT-PCR, which was further confirmed by flow cytometry." (PMID 37398311, 2023). "Consistently, re-expression of WT USP22, but not its mutants restored integrin b1 expression in USP22-null breast cancer cells." (PMID 37398311, 2023). "Collectively, our study identified USP22 as a FoxM1-specific deubiquitinase which promotes FoxM1 transcriptional activation for ITGB1 expression, which consequently promotes breast cancer stem cell self-renewal and drives breast cancer metastasis to distal organs including lung." (PMID 37398311, 2023). "USP22 stabilizes c-Myc by removing the poly-ubiquitin chains and antagonizing the ubiquitination activity of its E3 ligase, FBW7, and consequently promoting breast cancer cell growth." (PMID 34575114, 2021). "Apart from facilitating c-Myc-driven transcription, USP22 also increases breast cancer cell proliferation partly through its nontranscriptional activity on regulating the cell cycle machinery and promoting the G1-S transition." (PMID 34575114, 2021). "Together, we discovered that HSP90AB1 is USP22-dependent and that cooperative targeting of USP22 and HSP90 may provide an effective approach to the treatment of colorectal and breast cancer." (PMID 31801945, 2019). "Similarly, diminished USP22 expression and/or RNF20/40 overexpression is observed in 37% of breast cancers and 34% of esophagus cancers." (PMID 29210986, 2017). "Finally, we examined ERBB2 levels with and without USP22 depletion in two HER2-positive human breast cancer cell lines, SKBR3 and HCC1954, and again saw no impact on ERBB2 protein levels upon USP22 loss." (PMID 38236941, 2024). "We then focused on studying the functional consequences of USP22-mediated integrin b1 upregulation and assessed whether USP22 maintains breast CSC self-renewal and promotes breast cancer metastasis through integrin b1 upregulation by ectopic reconstitution of ITGB1 in USP22 knockout cells." (PMID 37398311, 2023). "Importantly, treatment of USP22-null breast cancer cells did not further reduce the frequency of breast cancer stem cells, supporting the high specificity of this USP22-specific small molecule inhibitor." (PMID 37398311, 2023). "Consequently, expression of integrin b1 largely, but not totally restored 4T1 breast cancer lung metastasis of USP22-null cells as documented by analyzing both lung tumor nodule numbers and the metastatic foci size." (PMID 37398311, 2023). "Our data collectively documented that USP22 maintain breast cancer stemness in part through stabilizing ITGB1 transcription factor FoxM1 to promote breast cancer growth and metastasis, which define a previously unknown USP22-FoxM1-ITGB1 pathway in breast cancer pathogenesis." (PMID 37398311, 2023). "This is likely explained by regulation of PD-L1 by USP7 and USP22 in a tumor type–specific manner, since we have shown previously that CRISPR targeted USP22 deletion resulted in PD-L1 downregulation in human breast cancer cells but not in B16 cells." (PMID 38038129, 2023).
pancreatic cancer (19 papers, 2017 to 2026). "Research has demonstrated that eliminating USP22 from pancreatic tumor cells enhances the immune response by decreasing suppressive myeloid cells and increasing cytotoxic T cells and natural killer cells." (PMID 39048965, 2024). "Targeting USP22 in pancreatic cancer can enhance the effectiveness of immunotherapy and improve treatment outcomes." (PMID 39048965, 2024). "USP22 is highly expressed at the mRNA and protein levels in 14 common solid tumours, including pancreatic cancer, gastrointestinal tumours and liver cancer." (PMID 39661501, 2024). "Among them, USP22 was selected in a previous study which demonstrated that USP22 served as a cancer-promoting gene in the progression of pancreatic cancer." (PMID 35039872, 2022). "Taken together, our results indicated that USP22 induced p21 expression by deubiquitinating PTEN in pancreatic cancer." (PMID 34743406, 2022). "For example, the function of CTBP1-AS2/miR-141-3p/USP22 in pancreatic cancer needs to be verified with in vivo experiment." (PMID 35039872, 2022). "The expression of PTEN was induced by ubiquitin‐specific peptidase 22 (USP22) in pancreatic cancer, which depended on the deubiquitinating function of USP22." (PMID 34743406, 2022). "Collectively, the present study revealed that CTBP1-AS2 was an oncogenic lncRNA by regulating miR-141-3p/USP22 axis in pancreatic cancer." (PMID 35039872, 2022). "Because PTEN is critical for inhibiting pancreatic cancer progression, we employed RNA‐seq analysis to identify the underlying mechanism by which PTEN‐deubiquitinated USP22 regulates carcinogenesis." (PMID 34743406, 2022). "Reverse transcription-quantitative PCR was performed to assess the expression levels of CTBP1-AS2, microRNA (miR)-141-3p and ubiquitin-specific protease 22 (USP22) mRNA in pancreatic carcinoma tissues and cell lines." (PMID 35039872, 2022). "CTBP1-AS2 expression increased pancreatic carcinoma cell proliferation, migration and invasion and repressed apoptosis by regulating miR-141-3p/USP22 axis." (PMID 35039872, 2022). "The present study revealed that USP22 expression was markedly elevated in pancreatic carcinoma cell lines and tumor tissues." (PMID 35039872, 2022). "miR-141-3p expression was negatively correlated with USP22 mRNA expression, and CTBP1-AS2 expression was positively correlated with USP22 mRNA expression in pancreatic carcinoma tissues." (PMID 35039872, 2022). "In pancreatic cancer cells, mir-29c directly targets and down-regulates USP22, increasing chemotherapy sensitivity and inducing apoptosis by inhibiting USP22-mediated autophagy." (PMID 34769343, 2021). "Our published research has demonstrated that USP22 was related to the chemotherapy resistance to gemcitabine in pancreatic cancer." (PMID 28567015, 2017). "Conversely, USP22 overexpression facilitates the G1/S transition and leads to an S-phase accumulation in pancreatic cancer cell lines." (PMID 29210986, 2017). "In addition, an in vitro study using pancreatic cancer cells showed that downregulation of USP22 reduced cell stemness and enhanced drug sensitivity by inactivating the Wnt/β‐catenin pathway." (PMID 41541703, 2026). "Additionally, USP22 only plays a role in promoting the nuclear entry of β‐catenin in pancreatic cancer." (PMID 39661501, 2024). "USP22 induces the occurrence of EMT in pancreatic cancer cells by activating FAK signaling." (PMID 36902253, 2023). "The MTS assay and colony forming assays showed that USP22 silencing significantly inhibited the cell proliferation ability of pancreatic cancer cells, which could be reversed by PTEN overexpression." (PMID 34743406, 2022). "In addition, the downstream signaling pathway of USP22 in pancreatic cancer also needs to be investigated in the future." (PMID 35039872, 2022). "By inducing deubiquitination and inhibiting the degradation of PTEN, USP22 could also induce p21 expression in pancreatic cancer." (PMID 34743406, 2022).
pancreatic cancer (continued). "In addition, ubiquitin‐specific peptidase 22 (USP22) induced p21 expression by deubiquitinating PTEN in pancreatic cancer." (PMID 34743406, 2022). "Thus, restoration of USP22 expression is a novel therapeutic strategy to induce PTEN expression in pancreatic cancer." (PMID 34743406, 2022). "Because we demonstrated that USP22 deubiquitinated PTEN and inhibited the degradation of PTEN, we hypothesized that USP22 induced p21 expression via PTEN in pancreatic cancer." (PMID 34743406, 2022). "In addition, USP22 was shown to induce cell cycle protein-dependent kinase inhibitor 1A (CDKN1A) in pancreatic cancer, and MDM2 inhibitors enhanced the anti-pancreatic cancer effect of USP22 overexpression." (PMID 35884607, 2022). "Moreover, upregulation of miR-23b levels in radioresistant PDAC leads to sensitization of tumor cells to radiotherapy, while enhancement of miR-29c regulates USP22 increases the sensitivity of pancreatic cancer cells to chemotherapy." (PMID 36292753, 2022). "Therefore, a clearer understanding of methods to enhance anticancer effects and inhibit the cancer‐promoting potential of USP22 would provide new treatment options for pancreatic cancer." (PMID 34743406, 2022). "Collectively, these findings validated the hypothesis that CTBP1-AS2 could function as a ceRNA to facilitate pancreatic carcinoma cell proliferation, migration and invasion by adsorbing miR-141-3p and upregulating USP22 expression." (PMID 35039872, 2022). "Furthermore, USP22 knockdown in pancreatic carcinoma cells can promote the infiltration of T cells and natural killer cells in the tumor microenvironment." (PMID 35039872, 2022). "Notably, USP22 expression levels were significantly enhanced in pancreatic carcinoma cell lines and tumor tissues (respectively)." (PMID 35039872, 2022). "In conclusion, lncRNA CTBP1-AS2 may be involved in pancreatic carcinoma progression by regulating miR-141-3p and USP22 expressions; in addition, CTBP1-AS2 may be a diagnostic biomarker and treatment target for pancreatic carcinoma." (PMID 35039872, 2022). "The rescue assays showed that the inhibiting effects of CTBP1-AS2 knockdown on pancreatic carcinoma cell proliferation, migration, invasion and apoptosis could be reversed by USP22 overexpression." (PMID 35039872, 2022). "Western blotting was used to examine USP22 protein expression in pancreatic carcinoma cell lines." (PMID 35039872, 2022). "In addition, in a pancreatic cancer cell line (Panc-1), USP22 overexpression stimulates autophagy through the ERK1/2 pathway and hereby promotes resistance to gemcitabine treatment." (PMID 29210986, 2017). "In pancreatic cancer cell lines, an alternative mechanism was reported, whereby USP22 was found to modulate the β-catenin/Wnt signaling and thus increase the abundance of FoxM1, a transcription factor that normally represses the expression of two CDK inhibitors, p21 and p27." (PMID 29210986, 2017). "Furthermore, the overexpression of USP22 could inhibit the progression of pancreatic cancer by inducing PTEN expression." (PMID 34743406, 2022). "Therefore, USP22 deubiquitinated PTEN and inhibited the degradation of PTEN; upregulation of USP22 expression could restore PTEN expression in pancreatic cancer." (PMID 34743406, 2022).
pancreatic cancer (continued). "Therefore, our study indicated that both PTEN and USP22 could be novel therapeutic targets for pancreatic cancer." (PMID 34743406, 2022). "The ubiquitin-specific peptidases (USPs) are the primary members of the deubiquitinase family, where USP22 and USP28 are overexpressed in pancreatic cancer cells." (PMID 36902253, 2023). "Taken together, USP22 could also induce the expression of p21 via deubiquitinating and upregulating the expression of PTEN in pancreatic cancer." (PMID 34743406, 2022). "Ubiquitin specific peptidase 22 (USP22) is an epigenetic regulator, it was reported USP22 induced autophagy by activating MAPK1, thereby promoting cell proliferation and gemcitabine resistance in pancreatic cancer cell lines." (PMID 36263211, 2022). "Importantly, in pancreatic carcinoma, USP22 is overexpressed and promotes migration, invasion and EMT of pancreatic carcinoma cells through the focal adhesion kinase pathway." (PMID 35039872, 2022). "According to the results of previous studies, USP22 can induce EMT by regulating TGF-β1 in lung cancer cells, and elevated USP22 expression can promote EMT by up-regulating ZEB1 and Snail in pancreatic cancer cells though a process that involves focal adhesion kinase (FAK) signaling." (PMID 28427243, 2017). "Furthermore, by inducing deubiquitination and inhibiting the degradation of PTEN, USP22 could induce cyclin‐dependent kinase inhibitor 1A (CDKN1A, also symboled as p21) expression in pancreatic cancer." (PMID 34743406, 2022). "In addition, MTS, apoptosis, and cell cycle assays indicated the enhanced effects of USP22 overexpression and MDM2 inhibitor treatment in the inhibition of proliferation, and the induction of apoptosis and cell cycle arrest, in pancreatic cancer cells in vitro." (PMID 34743406, 2022). "Besides, USP22 was not a differential expressed gene in PTEN silenced pancreatic cancer cells." (PMID 34743406, 2022). "Furthermore, to determine that USP22 regulated the progression of pancreatic cancer by regulation PTEN expression, pancreatic cancer cells with or without USP22 silencing were infected with pcDNA3.1 or PTEN plasmids." (PMID 34743406, 2022).
gastric cancer (18 papers, 2017 to 2025). A primary or metastatic malignant neoplasm involving the stomach. "This study aimed to investigate the role of USP22 and the underlying mechanism in human gastric cancer." (PMID 32063746, 2020). "To investigate the mechanism underlying the oncogenic role of USP22 in gastric cancer, we performed a ChIP-seq assay and found 16 differentially expressed genes in USP22-overexpressing SGC7901 cells, compared with control cells." (PMID 32063746, 2020). "Gain- and loss-of-function assays showed that USP22 promoted gastric cancer cell growth and cell cycle transition while suppressing apoptosis in vitro." (PMID 32063746, 2020). "In this study, we detected a positive correlation between USP22 expression and T stage in 88 patients with gastric cancer, suggesting that USP22 expression is associated with gastric tumor growth." (PMID 32063746, 2020). "For example, in stomach cancer, increased USP22 in cancer tissues was associated with shorter patient survival." (PMID 31842906, 2019). "Increased ubiquitin-specific protease 22 (USP22) has been associated with poor prognosis in several cancers including gastric cancer." (PMID 28415621, 2017). "To further evaluate the potential prognostic values of USP22 expression and other clinical characteristics in gastric cancer, we determined the association of these variables with the overall survival of patients using Kaplan–Meier analysis and the log-rank test." (PMID 32063746, 2020). "In addition, the presence of USP22 was positively correlated with T stage in patients with gastric cancer, suggesting that USP22 expression is associated with gastric tumor growth." (PMID 32063746, 2020). "Subsequently, immunohistochemistry (IHC) and RT-qPCR-based studies found USP22 abundance to be higher in cancerous than normal samples and associated with worse patients outcomes in multiple cancer types including colorectal, breast, esophageal, ovarian, pancreatic and stomach cancers." (PMID 29210986, 2017). "Previous studies demonstrated that USP7, USP9X and USP22 stabilize PD-L1 in gastric cancer, oral squamous cell carcinoma or liver cancer, respectively." (PMID 38167274, 2024). "Studies have shown that the tumor suppressor miR-4490 can bind to sequences within the 3′-UTR of USP22 and inhibit the expression of USP22 in gastric cancer cells." (PMID 35935969, 2022). "In gastric cancer, USP22 expression is significantly upregulated; it can promote cancer cell proliferation and inhibit apoptosis through regulating son of sevenless 1/RAS protein axis." (PMID 35039872, 2022). "Through clinical specimen analysis, overexpression of USP22 and BMI1 was associated with gastric cancer progression and treatment failure." (PMID 35935969, 2022). "USP22 also promoted gastric cancer progression and metastasis through regulating c-Myc/NAMPT/SIRT1-dependent FOXO1 and YAP signaling." (PMID 34753387, 2021). "USP22-overexpressing SGC7901 and USP22-silencing AGS cells were used to explore the role of USP22 in gastric cancer cell behavior in vitro and in vivo." (PMID 32063746, 2020). "We also investigated the effects of USP22 overexpression and knockdown on the malignant behavior of gastric cancer cells in vitro and in vivo." (PMID 32063746, 2020). "USP22 acts as an oncogene in gastric cancer, as evidenced by the enhancement of aggressive cancer cell behavior induced by USP22 overexpression." (PMID 32063746, 2020). "In this study, by assessing the expression of USP22 in 88 paired samples of primary gastric tumor tissue and adjacent normal tissue, we demonstrated that USP22 is predominantly expressed in gastric cancer tissue." (PMID 32063746, 2020). "Our results indicate that USP22 promotes cell proliferation, migration, invasion, and cell cycle transition, while inhibiting apoptosis in gastric cancer cells." (PMID 32063746, 2020).